CD28 (CD28 molecule)
Diseases named in the same sentence as CD28 in open-access papers (continued):
Sharing a sentence is not in itself a finding about the gene and the disease.
Sepsis (continued). "The ability of CD28 to regulate inflammation in the innate immune response to sepsis is consistent with prior reports documenting CD28 expression on PMNs and the ability of CD28, either soluble or in PMN lipid rafts, to induce NF-κB and pro-inflammatory cytokine production via CD80/CD86." (PMID 19672303, 2009). "Thus, in the previously published study we surmised that CD4+ Foxp3+ IL-10-producing cells could be mechanistically responsible for the observed increase in sepsis survival in CD28 agonist-treated animals." (PMID 38633258, 2024). "This pluripotent cytokine can mitigate lymphocyte apoptosis by enhancing the expression of anti-apoptotic proteins such as Bcl-2, CD-28, boosting IFN-γ levels, and increasing TCR diversity, which are typically diminished in patients with sepsis." (PMID 39720718, 2024). "We also found that the expression level of CD3D, CD3E, CD4, CD28, IL7R, and LCK was statistically different between sepsis and normal groups, indicating their potential role in the development of sepsis." (PMID 37113759, 2023). "The results showed the expression level of CD3D, CD3E, CD4, CD28, IL7R, and LCK was statistically different between sepsis and normal groups." (PMID 37113759, 2023). "The lower expression of the hub genes (CD3D, CD3E, CD4, CD28, IL7R and LCK) was observed in sepsis samples, which was consistent in all the six hub genes." (PMID 37113759, 2023). "The lower expression of the six hub genes (CD28, CD3D, CD4, IL7R, LCK, and CD3E) was observed in sepsis samples." (PMID 37113759, 2023). "Among the genes identified through the PPI network, many genes such as MPO, CD28, and TLR8 have been reported to play a vital role in sepsis." (PMID 35739592, 2022). "We also found that, among all active CMV–infected patients with sepsis, those with a lower CD8+CD28+ T‐cell count had less CMV‐DNA–negative conversion and a higher 28‐day mortality after enrollment." (PMID 36106958, 2022). "However, whether the expression of CD28 changes during sepsis is still debated." (PMID 33717146, 2021). "2B4 and CD28 expression on CD4 + and CD8 + T cells were tested on days 1, 3 and 7 after sepsis diagnosis." (PMID 34781995, 2021). "We compared the mean fluorescence intensity (MFI) of CD69 and CD28 expression on gated CD4+ T and CD8+ T cells in the two sepsis models." (PMID 33717146, 2021). "Fungal Candida infected sepsis patients also demonstrate an increased PD-1 expression on circulating CD4 and CD8 T cells, and decreased CD28 expression." (PMID 33613563, 2020). "Circulating MDSCs from 267 survivors of surgical sepsis were phenotyped at various intervals over 6 weeks, and highly enriched MDSCs from 23 of these samples were co-cultured with CD3/CD28-stimulated autologous T cells." (PMID 31722736, 2019). "Upregulation of coinhibitory molecules, PD-L1 and PD-1, and downregulation of positive costimulatory molecules, CD28, CD80, and CD86, are the features of sepsis-induced immunosuppression, reversal of which will improve the survival of septic mice." (PMID 24891762, 2014). "For example, CD4+/CD8+ lymphocytes collected from patients deceased during acute sepsis feature reduced cytokine production and activation marker expression in response to soluble CD3/CD28 mAb mediated TCR/co-receptor stimulation." (PMID 25541945, 2014). "To investigate the potential role of PD-1/PD-L1 on T-cell apoptosis in sepsis, we induced the apoptosis under stimulation with exogenous recombinant TNFα or anti-CD3 and anti-CD28 ligation." (PMID 21349174, 2011). "Together suggesting CD28, through either CD80 or CD86 is capable of mediating the inflammatory response and lethality of polymicrobial sepsis." (PMID 19672303, 2009). "Studies also found that an increased PD-1/CD28 ratio on CD8+ T cells, rather than the PD-1 expression level alone, better predicts the risk of nosocomial infection in sepsis patients." (PMID 41462924, 2025).
Sepsis (continued). "As such, T cell stimulator (anti-CD3 and anti-CD28 dyna-bead) was incubated in the PBMC and isolated CD3 + T cells from patients with sepsis and healthy control for 4 days, and T cell proliferation was evaluated using carboxyfluorescein succinimidyl ester (CFSE) staining." (PMID 40108283, 2025). "In a cancer–sepsis model, PD-1 blockade did not confer a survival advantage and was associated with a loss of CXCR5+PD-1+ T cells and decreased CD28 expression, whereas blockade of another checkpoint receptor (2B4) significantly improved outcomes." (PMID 41462924, 2025). "Key markers of immune dysfunction in sepsis, such as HLA-DR expression on monocytes, T cell activation/exhaustion markers (e.g., CD28, CD38), were not assessed." (PMID 41346598, 2025). "After activation with anti-CD3/CD28 antibodies, flow cytometry analysis showed that CD4+ T cells from sepsis patients produced significantly less interleukin-2 (IL-2) and interferon (IFN-γ), suggesting that these cells are functionally suppressed and exhausted." (PMID 41306770, 2025). "CD4, CD8A, CD28, CD2, CD3E as T cell surface active molecules play important roles in the immune response process; among them, the roles of CD4 and CD8 T lymphocytes in sepsis have been widely recognized." (PMID 39654893, 2024). "CD28 is a T cell costimulatory receptor which, upon ligation with CD80/CD86, transmits a costimulatory signal important for T cell activation, proliferation, and pro-inflammatory responses, making it a potential target for sepsis immunomodulatory therapy." (PMID 38633258, 2024). "We previously demonstrated that CD28 agonism results in improved sepsis survival in immunologically experienced, but not naïve, hosts." (PMID 38633258, 2024). "Notably, HLA DR+ CD8br %T cells and CD127 on CD28+ CD45RA- CD8br T cells emerged as common immune cell traits, serving as outcomes in AP and exposures in sepsis." (PMID 38601150, 2024). "Several previous studies have demonstrated the CD28, CD3, CD4 molecules in sepsis or septic shock." (PMID 39654893, 2024). "These conclusions are consistent with our research, as we found that the NK cell count, immunoglobulin G and the CD8+CD28+ T‐cell count in active CMV–infected patients with sepsis were significantly higher than in those without active CMV infection." (PMID 36106958, 2022). "Interestingly, T-cells from animals that had suffered an episode of SIRS or sepsis exhibited a significantly higher proliferative score than control T-cells when challenged with soluble CD3 and CD28 Abs, reminiscent of the activation marker profiles." (PMID 25541945, 2014). "In those model systems, there is a much more prominent role for CD4+ T-cells, as opposed to PMNs or soluble CD28 as observed in the early phases of sepsis." (PMID 19672303, 2009). "Consequently, the goals of this study were to determine the individual contribution of CD28, CD80 and CD86 to the inflammatory response in murine sepsis, and to better correlate expression of these molecules with outcome in humans with sepsis and septic shock." (PMID 19672303, 2009). "By and Large, increasing account of CD28+ DN Treg cells may increase the levels of the T-cell surface glycoprotein CD6 isoform and enhance the efficiency of Tregs to repress immune responses, aggravating sepsis." (PMID 39076981, 2024). "Furthermore, our mediating analysis revealed that effector memory T-cells (CD45RA- CD28- CD8br) could reduce the protein levels of S100A12, thereby exacerbating the severity of sepsis." (PMID 39076981, 2024). "Furthermore, the rate of IFNg production after anti-CD3/anti-CD28 stimulation did not significantly differ between sepsis and non-sepsis groups over the study period, although the mean cytokine concentrations did show notable differences between groups." (PMID 39712015, 2024).
Sepsis (continued). "However, the preponderance of studies analyzing the role of CD28 and/or its ligands CD80/86 in models in which the recipients used are immunologically naïve have demonstrated that deleting or antagonizing CD28 signaling results in improved sepsis mortality." (PMID 38633258, 2024). "The CMV‐DNA–negative conversion and 28‐day mortality of active CMV–infected patients with sepsis could be predicted using cutoff values of 151 (74.5% sensitivity and 87.1% specificity) and 64.5 (52.9% sensitivity and 92.3% specificity) CD8+CD28+ T cells mL−1 at ICU admission, respectively." (PMID 36106958, 2022). "Both the CD8+CD28+ and CD8+ T‐cell counts could be combined with the NK cell count, Acute Physiology and Chronic Health Evaluation II score and immunoglobulin G as related factors for active CMV infection in patients with sepsis." (PMID 36106958, 2022). "Secondly, the studies do not identify how IFN-γ production is suppressed in nonsurviving SEPSIS patients in response to anti-CD3/anti-CD28 mAb stimulation." (PMID 38100268, 2024). "The regression analysis showed that both the CD8+CD28+ and CD8+ T‐cell counts could be combined with the NK cell count, Acute Physiology and Chronic Health Evaluation II score and immunoglobulin G as related factors for active CMV infection in patients with sepsis." (PMID 36106958, 2022). "Much to our surprise, CD33+CD11b+HLA-DRlow/− cells isolated on day 4 after sepsis displayed a stimulatory, rather than suppressive, effect on lymphocyte proliferation to CD3/CD28 stimulation." (PMID 31722736, 2019). "In agreement with the activation marker and proliferation data, T-cells from animals with SIRS or sepsis were not impaired in the generation and release of IL-2 in response to soluble CD3 plus CD28 mAb." (PMID 25541945, 2014). "The acute phosphorylation/activation of ZAP-70, LAT, Erk or Akt in response to stimulation with immobilised or soluble CD3 and CD28 mAb was indistinguishable between control and any of the SIRS/sepsis groups." (PMID 25541945, 2014). "However, NK cell count, CD8+ T‐cell count, CD28+ T‐cell count and immunoglobulin G level in active CMV–infected patients with sepsis had significant differences compared with those in the nonactive CMV–infected group." (PMID 36106958, 2022). "In that study samples were isolated at day three to five of sepsis and stimulated with the non-specific mitogen, phytohemagglutinin (PHA), whereas we examined cells either at day one or day seven and activated with α-CD3/α-CD28 which more selectively induces T cell proliferation." (PMID 22742734, 2012).
breast cancer (49 papers, 2004 to 2026). A primary or metastatic malignant neoplasm involving the breast. "There was a difference in the rs3116496 polymorphism of the CD28 gene between breast cancer patients and controls in a Chinese Han population." (PMID 23133541, 2012). "Our findings indicate that CD28 gene polymorphisms contribute to sporadic breast cancer risk and have a significant association with clinicopathological features in a northeast Chinese Han population." (PMID 23133541, 2012). "In this case-control study, we genotyped SNPs that completely span the CD28 gene region, and we classified the association between CD28 gene variants and sporadic breast cancer in a Chinese Han population in Northeast China." (PMID 23133541, 2012). "The clinical features analysis in this study revealed an association between CD28 gene polymorphisms and prognostic factors in breast cancer, including ER and C-erbB2 status." (PMID 23133541, 2012). "Taken together, the current study shows that polymorphisms of the CD28 gene region may affect susceptibility to sporadic breast cancer risk in Chinese Han women." (PMID 23133541, 2012). "Given the association between polymorphisms in the CD28 gene region and cervical cancer risk in different populations, as well as the potential role of costimulatory molecules in carcinogenesis, we examined the association between CD28 polymorphisms and breast cancer risk and tumor pathology." (PMID 23133541, 2012). "Recent studies have shown that CD32/CD8a/CD28/CD3ζ chimeric receptor cells directly kill breast cancer cells, suggesting the existence of cell surface myeloid FcγR alternative ligands (ALs)." (PMID 39962623, 2025). "Superior anti-tumor efficacy of CD28 HD/TM was also reported in HER2-positive breast cancer and CD276-positive neuroblastoma." (PMID 37924157, 2023). "Stimulation of PBMCs from breast cancer patients with anti-CD3/anti-CD28 was sufficient to trigger CD39 expression." (PMID 35406703, 2022). "In the present study, human monocyte-derived macrophages (HMDMs) were stimulated with the conditioned medium (CM) of lymphocytes, the CM of lymphocytes activated with anti-CD3 and anti-CD28 antibodies, and the CM of breast cancer cell lines (BT-20 and MCF-7)." (PMID 35835809, 2022). "To target tumor-associated MUC1 on breast cancer cells, we have generated second-generation CAR MUC1 T cells with two differential costimulatory signals, that is, 41BB and CD28, and determine their immune characteristics and in vitro antitumor activities." (PMID 36457849, 2022). "We previously showed that the abundance of peripheral blood CD8 + CD28+ cytotoxic T lymphocytes is predictive of PFS in breast cancer, particularly in patients with HER2+ breast cancer who received anti-HER2 therapy." (PMID 36135052, 2022). "have reported that CD28 is irrelevant to metastatic NSCLC prognosis; however, the serum level of CD28 is higher in patients with breast cancer and has been identified as a novel prognostic indicator." (PMID 34367975, 2021). "A previous study reported increased CD8+CD28− T-cell counts and decreased CD8+CD28+ T-cell counts in the peripheral blood of breast cancer patients, relative to healthy controls." (PMID 30971280, 2019). "Inducible co-stimulator (ICOS) is a CD28-related molecule exclusively expressed on activated T cells and plays a critical role in modulating the immune response in breast cancer." (PMID 31143539, 2019). "In CD8 T cells, higher CD27 and CD28 expression was observed in controls compared to women with breast cancer (p = 0.001 and p < 0.0001, respectively)." (PMID 30061900, 2018). "Significance of this analysis is exemplified by the fact that mutations of BTLA, CD28, CD4, and CD8A genes in the GO term cell surface receptor-linked signal transduction contribute to sporadic breast cancer risk." (PMID 27911271, 2017).
breast cancer (continued). "Degree of CD28 expression in the CD4+ T-lymphocyte subset in different areas of the sentinel nodes from 21 breast cancer patients (numbers are frequencies)." (PMID 15613231, 2004). "Compared to healthy controls, breast cancer patients display significantly lower percentages of CD28+ T cells in peripheral blood." (PMID 15613231, 2004). "Degree of CD28 expression in the CD8+ T-lymphocyte subset in different areas of the sentinel nodes from 21 breast cancer patients (numbers are frequencies)." (PMID 15613231, 2004). "Moreover, targeting HER2 and CD3 in mass forming such as breast cancer using tri-specific cell engager molecules has been developed by adding further CD28 into another binding arm for co-stimulating T-cell response against HER2-positive breast cancer." (PMID 40918454, 2025). "To date, no prior studies have examined the role of CD28 expression in EC prognosis, though it has been implicated in stage and relapse in head and neck, lung, and breast cancers." (PMID 40136325, 2025). "Finally, we attempted to induce increased SLFN11 expression by co-culturing breast cancer cells with PBMC activated by CD3/CD28 for 24 h." (PMID 38001424, 2023). "HER2-CAR constructs were comprised of either CD28 or 4-1BB domains and demonstrated functional activity in vitro, as documented by the assessment of cytokine production, T-cell proliferation, and cytotoxicity against breast cancer cell line." (PMID 35093187, 2022). "Genotyping of CD28 gene SNPs in breast cancer patients and controls." (PMID 23133541, 2012). "Our data provides the first evidence for the involvement of the human CD28 gene in breast cancer." (PMID 23133541, 2012). "This study provides the first evidence for the involvement of the human CD28 gene in breast cancer." (PMID 23133541, 2012). "Recently, we showed that extracellular CD32 (CD28/CD3ζ)-reactive T cells recognize ALs and trigger HLA-unrestricted cytotoxicity in a subset of BC cells, including triple-negative breast cancer (TNBC) cells." (PMID 39962623, 2025). "Similarly to what was reported for breast cancer patients, high peripheral CD8+CD28+ T-cell levels are linked to better overall survival (OS) and PFS in adenocarcinomas, whereas squamous cell carcinomas (SCCs) with a high frequency of CD8+CD28− T cells tend to have worse OS and PFS." (PMID 39684559, 2024). "Furthermore, HER2‐expressing MDA‐MB468 breast cancer cell lines were successfully lysed in vitro by genetically engineered NK‐92‐scFv(FRP5)‐zeta cells producing a humanized CAR based on HER2‐specific antibody FRP5 carrying CD28 and CD3 signalling domain." (PMID 35762299, 2022). "No case-control study of CD28 gene polymorphisms in sporadic breast cancer has been reported." (PMID 23133541, 2012). "The integration of affinity-optimized scFv domains and selective costimulatory motifs (CD28, 4-1BB, or OX40) allows precise modulation of activation thresholds, improving both efficacy and safety in antigen-diverse breast cancer subtypes." (PMID 41348261, 2025). "Lower CD28 expression is a marker of T-cell senescence, and increased CD8+CD28− subset populations play heterogeneous roles in cancers such as lung cancer and breast cancer, but few studies have been related to NPC." (PMID 36721233, 2023). "Further studies in breast cancer xenograft mouse models are necessary to compare in vivo antitumor activity and in vivo persistence between anti-MUC-1 CAR T cells with a 4-1BB or CD-28 endosignaling domain." (PMID 36457849, 2022). "To evaluate in vitro anti-tumor effects based on the anti-PD-L1 mAb in the 4T1 mouse mammary carcinoma model, we measured the proliferation of CD8+ T cells after anti-CD3/CD28 antibody stimulation." (PMID 34885221, 2021). "Several CARs were engineered and the HMFG2 CAR containing a fused CD28 plus OX40 plus CD3 endodomain (HOX HMFG2) together with the IgD linker, to combat glycosylation-independent steric hindrance, was shown to inhibit breast cancer growth in a mouse model." (PMID 29784646, 2018).